NEDD4 (NEDD4 E3 ubiquitin protein ligase)
Diseases named in the same sentence as NEDD4 in open-access papers (continued):
Sharing a sentence is not in itself a finding about the gene and the disease.
lung disease (3 papers, 2021 to 2025). "NEDD4 is an E3 ubiquitin ligase that has recently been linked to inflammatory responses and oxidative stress, playing a crucial role in the pathogenesis of pulmonary diseases." (PMID 40182927, 2025). "Longitudinal micro-CT enables in vivo monitoring of the onset and progression and detects radiological key features of IPF-like lung disease in conditional Nedd4-2−/− mice." (PMID 39437758, 2024). "Similar to previous studies in conditional Nedd4-2−/− mice with advanced IPF-like lung disease, we found radiomorphological characteristics of consolidations, reticulations, traction bronchiectasis, and honeycombing-like lesions, resembling a UIP pattern in this mouse model." (PMID 39437758, 2024). "However, our study was not powered to detect gender differences, and future studies are necessary to determine the potential role of gender differences in ENaC-mediated Na+ absorption in the pathogenesis of lung disease in congenital Nedd4-2−/− mice." (PMID 34200296, 2021).
male infertility (3 papers, 2024 to 2025). The inability of the male to effect fertilization of an ovum after a specified period of unprotected intercourse. "The NEDD4 gene, encoding an E3 ubiquitin ligase, plays a role in mRNA metabolism and stress response, and its deficiency can lead to impaired spermatogenesis and male infertility." (PMID 38254422, 2024). "Collectively, we are the first to demonstrate that the YAP1/RAD21/NEDD4 pathway mediates the fate determinations of human SSCs and abnormality or mutations of YAP1 are associated with male infertility." (PMID 39659446, 2024). "Collectively, these results highlight a critical role of YAP1 in determining the fate determinations of human SSCs and male infertility through the YAP1/RAD21/NEDD4 pathway." (PMID 39659446, 2024).
schizophrenia (3 papers, 2019 to 2025). A major psychotic disorder characterized by abnormalities in the perception or expression of reality. "Consistent with the results of previous studies, our findings indicate a relation between NEDD4 and susceptibility to schizophrenia." (PMID 33897484, 2021). "Our previous study revealed that the rs2303579 and rs62043855 loci in NEDD4 are associated with cognitive dysfunction in schizophrenia patients in the Chinese Han population." (PMID 33897484, 2021). "In our research, the NEDD4 gene polymorphism of rs3088077 and rs2303579 loci was associated with schizophrenia in Chinese Han population." (PMID 31849325, 2019). "Current studies have shown that the NEDD4 gene is associated with many neuropsychiatric disorders, such as schizophrenia." (PMID 31849325, 2019). "Secondly, our study only analyzed the association between a single locus of the NEDD4 gene and cognitive dysfunction in schizophrenia." (PMID 31849325, 2019). "The abnormal expression of the NEDD4 gene may cause abnormalities in the nervous system, which may cause clinical symptoms in patients with schizophrenia." (PMID 33897484, 2021). "Therefore, a case-control study was conducted by our research group to investigate the relationship between the NEDD4 gene polymorphism and cognitive dysfunction in Chinese Han schizophrenia patients." (PMID 31849325, 2019). "It remains to be further studied whether this amino acid change affects the function of NEDD4 protein, and then leads to the deficiency of spatial working memory in patients with schizophrenia." (PMID 31849325, 2019). "A number of recent studies have shown that the polymorphism of the neural precursor cell expressed developmentally down-regulated 4 (NEDD4) gene is associated with a variety of neuropsychiatric disorders, such as schizophrenia, and may also be associated with cognitive dysfunction in these diseases." (PMID 31849325, 2019). "Using the GMDR, controlling for sex and age as covariates, we analyzed the interactions between NEDD4 and childhood abuse on symptoms of schizophrenia in five components of PANSS and seven dimensions of MCCB." (PMID 33897484, 2021). "Our findings not only confirmed the possible connection between NEDD4 and schizophrenia but also explored the optimal model of NEDD4 × childhood abuse interaction on schizophrenic clinical symptoms." (PMID 33897484, 2021). "Our study highlighted the importance of the combined interactions of NEDD4 and CT in the clinical symptoms of patients with schizophrenia." (PMID 33897484, 2021). "We also found that the interaction between NEDD4 and CT had a certain impact on the clinical symptoms of schizophrenia." (PMID 33897484, 2021). "Our previous studies have shown that multiple single-nucleotide polymorphisms (SNPs) of the NEDD4 gene may be associated with schizophrenia, and the TT genotype of rs7162435 locus may be associated with the clinical phenotype of excitement and hostility in patients with schizophrenia." (PMID 31849325, 2019). "However, to the best of our knowledge, the present study is the first to link the NEDD4 gene, CT, and schizophrenia." (PMID 33897484, 2021). "Given the current understanding of the biological function NEDD4, NEDD4 may be inferred to be related with the development of not only schizophrenia but also other mental diseases." (PMID 33897484, 2021). "There is indirect evidence supporting the inference that the NEDD4 gene might interact with CT for schizophrenia." (PMID 33897484, 2021). "Thus, the current study aimed to investigate the potential involvement of G × Es of NEDD4 and CT on the clinical symptoms of schizophrenia." (PMID 33897484, 2021). "Distribution of 5 SNPs in NEDD4 in patients with schizophrenia and controls." (PMID 33897484, 2021). "Our results indicated that the interaction between NEDD4 and CT may play an essential role in the development of the clinical symptoms of schizophrenia." (PMID 33897484, 2021).
schizophrenia (continued). "However, the relationship among the amino acid residues changing, NEDD4 protein and the impairment of the ability to reason and solve the problem in schizophrenia patients still remains to be further studied." (PMID 31849325, 2019). "Current research on the NEDD4 gene and cognitive dysfunction of schizophrenia is rare." (PMID 31849325, 2019). "At present, studies have shown that the NEDD4 gene may be related to the pathological process of schizophrenia." (PMID 31849325, 2019). "However, whether NEDD4 interacts with CT on symptoms of schizophrenia remains unknown." (PMID 33897484, 2021).
Sepsis (3 papers, 2021 to 2025). Sepsis is defined as life-threatening organ dysfunction caused by a dysregulated host response to infection. "The nomogram illustrates the individual contributions of the five genes (TXN, MAPK14, WIPI1, CD82, and NEDD4) and clinical information (age, gender) to the overall risk score, providing a practical tool for estimating the probability of sepsis." (PMID 40299574, 2025). "For example, TXN and MAPK14 are expressed predominantly in monocytes, whereas WIPI1, CD82, and NEDD4 exhibit variable expression in T and B cells, highlighting the diversity and composition of immune populations during sepsis." (PMID 40299574, 2025). "Taken together, diclofenac, flurbiprofen, and N-acetyl-L-cysteine may regulate ferroptosis and cellular-senescence-related pathways through specific binding to MAPK14, TXN, and NEDD4, thus providing potential pharmacological intervention strategies for sepsis treatment." (PMID 40299574, 2025). "The merged dataset (GSE57065 and GSE65682) revealed that all five genes (CD82, MAPK14, NEDD4, TXN, and WIPI1) were significantly upregulated in the sepsis group compared with the control group." (PMID 40299574, 2025).
bladder tumor (2 papers, 2019 to 2020). "Increasing levels of NEDD4 significantly reduced PTEN expression, and potentiated cell proliferation and prostate/bladder tumor formation, suggesting an oncogenic role for NEDD4-1 in regulating PTEN functions." (PMID 31856858, 2019).
breast tumor (2 papers, 2016 to 2019). "To determine the potential molecular mechanisms by which NEDD4 promotes breast tumor growth and progression, we determined the expression of NEDD4 along with PTEN, IGF-1R, and p-Akt by IHC using a TMA that consisted of 148 samples of early-stage primary invasive breast cancer." (PMID 31856858, 2019).
cholangiocarcinoma (2 papers, 2024 to 2025). A carcinoma that arises from the intrahepatic biliary tree (intrahepatic cholangiocarcinoma) or from the junction, or adjacent to the junction, of the right and left hepatic ducts (hilar cholangiocarcinoma). "NEDD4 promotes cholangiocarcinoma progression by targeting FBP1 and inhibiting its expression through ubiquitination." (PMID 40100307, 2025). "Two NFATc2-related axes control cancer progression: the NEDD4/FBP1 axis in cholangiocarcinoma and the MYC/NFATc2 axis in acute myeloid leukemia (AML) cells." (PMID 39822413, 2024). "NFATc2 is involved in the cholangiocarcinoma progression via the NEDD4/FBP1 axis." (PMID 39822413, 2024). "In cholangiocarcinoma, NFATC2 can be enriched in the promoter region of the developmentally downregulated protein 4 (NEDD4) expressed in neural precursor cells to promote its expression." (PMID 40100307, 2025). "In addition, NEDD4 targets FBP1 and inhibits its expression through ubiquitination, thereby promoting cholangiocarcinoma progression." (PMID 40100307, 2025).
colorectal tumors (2 papers, 2022 to 2023). "Although NEDD4 depletion does not promote tumor development on its own, it does cause tumor growth enhancement in Apc+/min-derived colorectal tumors, implying that NEDD4 typically reduces intestinal Wnt signaling and colonic tumorigenesis." (PMID 36293239, 2022). "In vivo experiment has found that knockout of NEDD4 augments colorectal tumor growth in APC+/min mice." (PMID 36831013, 2023). "In addition, NEDD4 mediates LGR4/5 and DVL2 lysosomal and proteasomal degradation, resulting in inactivation of the WNT/β-catenin signaling pathway and inhibition of the susceptibility and progression of colorectal tumors." (PMID 36831013, 2023).
deafness (2 papers, 2018 to 2025). An inherited or acquired condition characterized by the complete loss of the ability to hear from one or both ears. "Expressed broadly within the cochlear duct, NEDD4 encodes a ubiquitin ligase protein known for its interaction with and ubiquitination of products from diverse genes associated with deafness." (PMID 40353062, 2025). "We have identified putative causal variants in known deafness genes and several novel candidate genes, including NEDD4 and NEFH that were mutated in multiple individuals." (PMID 30180840, 2018). "Therefore, NEDD4 may serve as novel candidate deafness gene." (PMID 40353062, 2025).
depression (2 papers, 2019 to 2021). "Indeed, a recent article explored the possible relation between NEDD4 and depression." (PMID 33897484, 2021). "Whether the strengthening effect of NEDD4 on the negative environment has a role in other mental and psychological diseases, such as depression, needs to be explored further." (PMID 33897484, 2021). "However, clinical studies on the correlation between NEDD4 and depression have not been conducted." (PMID 33897484, 2021).
endometrial cancer (2 papers, 2022 to 2023). Primary or metastatic malignant neoplasm involving the endometrium (mucous membrane that lines the endometrial cavity). "The levels of FOXM1, an oncogenic transcription factor, are positively correlated with NEDD4 expression in endometrial cancers." (PMID 36293239, 2022). "In addition, NEDD4 overexpression in endometrial cancer cells enhanced IGF-1R cell surface localization, Akt activation, and cell proliferation." (PMID 36293239, 2022). "NEDD4-mediated ubiquitination regulates the levels of phosphorylated AKT, but not of total AKT, in MCF−7 and endometrial cancer cells." (PMID 36672488, 2023).
gastric tumor (2 papers, 2021 to 2023). "We found that Dox-induced NEDD4 reduction significantly inhibits gastric tumor growth in vivo." (PMID 36774408, 2023).
leukemia (2 papers, 2024). A malignant (clonal) hematologic disorder, involving hematopoietic stem cells and characterized by the presence of primitive or atypical myeloid or lymphoid cells in the bone marrow and the blood. "Satb1 has previously been shown to be associated with heightened hematopoietic stem cell (HSC) self-renewal, whereas the role of Tubb2a, Cnn3, Nedd4, and Cand2 in hematopoiesis and/or leukemia is poorly described." (PMID 38555405, 2024). "We first analysed the DA1-3b leukemia model and among the 70 commonly mutated genes in dormant leukemia DA1-3b/D365 and parental DA1-3b cells, ten genes (Ttc7b, Dnmt3b, Ap1b1, Ne1, Nedd4, Acy1, Cyp11a1, Htr2c, Magee1 and Gdi1) were amplified in dormant and parental cells." (PMID 39223638, 2024).
Liddle syndrome (2 papers, 2015 to 2020). A rare genetic form of low-renin hypertension characterized by hypertension associated with decreased plasma levels of potassium and aldosterone. "As a possible limitation of the Nedd4-2−/− mouse as a model for Liddle syndrome, one should consider that Nedd4-2 also regulates other proteins in the brain, such as neuronal voltage-gated sodium channels." (PMID 25991719, 2015).
liver cancer (2 papers, 2015 to 2022). An epithelial or non-epithelial malignant neoplasm that arises from the liver. "Moreover, NEDD4 knockdown in liver cancer cells increased PTEN and E-cadherin and decreased vimentin and p-Akt." (PMID 36293239, 2022). "Similarly, in QGY7703 and SMMC7721 liver cancer cells, the overexpression of NEDD4 suppressed LATS1, which results in enhanced cell proliferation." (PMID 36293239, 2022). "Similarly, in QGY7703 and SMMC7721 liver cancer cells, NEDD4 acts as an oncoprotein, and overexpression of this protein was shown to suppress apoptosis via partially increasing large tumor suppressor kinase 1 (LATS1) expression." (PMID 36293239, 2022).
liver disease (2 papers, 2024 to 2025). "A unique regulatory mechanism in liver disease was suggested by the study, which also found a distinct modification in the lactylation of NEDD4 by lactate, which further affected the functional dynamics between NEDD4 and Caspase-11." (PMID 39968078, 2025).
lymph node metastasis (2 papers, 2019 to 2022). "Most importantly, via the evaluation of NEDD4 expression in a subset of DCIS, IDC, and BC cases with lymph node metastasis (BCLNM) tumors, a gradually increased proportion of NEDD4 staining was observed to the advantage of BC." (PMID 31856858, 2019). "NEDD4 expression is an independent predictive factor for OS and DFS, particularly in BC patients with invaded lymph node metastasis." (PMID 31856858, 2019). "Results revealed a significant correlation between the expression of NEDD4 and KLF8 and clinical-grade and lymph node metastasis, yet neither patient age nor sex was correlated with the expression of NEDD4 and KLF8." (PMID 35031788, 2022). "We evaluated NEDD4 expression levels in DCIS (n = 37), IDC (n = 226) without lymph node metastasis, and BC with lymph node metastasis tumors (BCLNM, n = 182)." (PMID 31856858, 2019). "Strikingly, the proportion of cases showing NEDD4-positive staining increased to 51.4% (19/37) in DCIS, 58.4% (132/226) in IDC without lymph node metastasis, and 73.1% (133/182) in BC with lymph node metastasis (BCLNM)." (PMID 31856858, 2019).
metastatic melanoma (2 papers, 2020 to 2022). A melanoma that has spread from its primary site to another anatomic site. "Moreover, GITR is correlated with the activity of E3 ubiquitin protein ligase neural precursor cell expressed developmentally down-regulated protein 4 (NEDD4), often involved in metastatic melanoma." (PMID 35334544, 2022).
multiple sclerosis (2 papers, 2023 to 2025). A progressive autoimmune disorder affecting the central nervous system resulting in demyelination. "We evaluated the impact of Nedd4 deficiency on mouse T cell development and differentiation using flow cytometry and siRNA transfection, and subsequently validated these findings in T cells from patients with multiple sclerosis (MS)." (PMID 39972304, 2025). "Targeting NEDD4 in humans may offer a promising therapeutic strategy for the treatment of Th17-mediated autoimmune diseases, including multiple sclerosis." (PMID 39972304, 2025). "Furthermore, studies in mouse demyelination models and white matter lesions in patients with multiple sclerosis have demonstrated the role of the Nedd4-VHL pathway in remyelination; in particular, Nedd4 is required for differentiation and myelination of oligodendrocytes." (PMID 36835292, 2023).
myocardial ischemia (2 papers, 2023 to 2024). A disorder of cardiac function caused by insufficient blood flow to the muscle tissue of the heart. "Surprisingly, post-myocardial ischemia reperfusion resulted in greater increased lethality, attenuated microvascular injury and myocardial infarct size in NEDD4 KO mice, indicating a novel role of NEDD4 in myocardial reperfusion injury." (PMID 36732831, 2023). "Here, we also detected increase inflammatory cells infiltration and inflammation in NEDD4 KO mice post-myocardial ischemia reperfusion or pro-inflammatory stimulus." (PMID 36732831, 2023). "NEDD4-1, a widely known E3 ubiquitin protein ligase of PTEN, has diverse effects on cardiovascular diseases, including cardioprotective effects following myocardial ischemia‒reperfusion injury and regulation of vascular calcification by modulating bone formation signals." (PMID 39237902, 2024).
nephrogenic diabetes insipidus (2 papers, 2017 to 2021). Nephrogenic diabetes insipidus (NDI) is characterized by polyuria with polydipsia, recurrent bouts of fever, constipation, and acute hypernatremic dehydration after birth that may cause neurological sequelae. "In the rat kidney inner medulla, withdrawal of dDAVP increased the abundance of the NEDD4 E3-ligase, while lithium-induced nephrogenic diabetes insipidus coincides with reduced NEDD4 abundance." (PMID 28931009, 2017).
pancreatic adenocarcinoma (2 papers, 2017 to 2023). "We investigated the expression of NEDD4 and the tumor suppressor PTEN in normal immortalized human pancreatic duct epithelial cell line and pancreatic adenocarcinoma (PDAC) cell lines." (PMID 28423617, 2017).
preeclampsia (2 papers, 2024 to 2025). Preeclampsia is a hypertensive disorder of pregnancy that is characterized by new-onset hypertension with proteinuria presenting after 20 weeks of gestation, and depending on mild or severe forms may initially present with severe headache, visual disturbances, and hyperreflexia. "In the context of preeclampsia, NEDD4 is involved in the regulation of trophoblast necrosis by mediating the ubiquitination of TAK1, thereby affecting placental development and function." (PMID 41220585, 2025).
tuberculosis (2 papers, 2023 to 2025). A chronic, recurrent infection caused by the bacterium Mycobacterium tuberculosis. "The results showed that PLTP, RNASEL, SEMA7A, and TAPBP were upregulated in the whole blood of tuberculosis patients, while NEDD4 and THBS1 were downregulated." (PMID 40182927, 2025). "The discovery of these six mRNAs (NEDD4, PLTP, RNASEL, SEMA7A, TAPBP, and THBS1) not only reveals critical molecular mechanisms underlying immune regulation in tuberculosis but also establishes a robust theoretical foundation for advancing diagnostic and therapeutic strategies." (PMID 40182927, 2025). "NEDD4, PLTP, RNASEL, SEMA7A, TAPBP, and THBS1 were combined into a 6-mRNA feature panel for diagnosis of tuberculosis." (PMID 40182927, 2025).
acute kidney injury (1 paper, 2025). Sudden and sustained deterioration of the kidney function characterized by decreased glomerular filtration rate, increased serum creatinine or oliguria. "In a gentamicin-induced acute kidney injury experiment in rats, expression of MuRF1 and MAFbx was increased in muscle and correlated with AKI severity, whereas the expression of the other three E3 ligases (Nedd4, Trim32, and Fbxo30 / MUSA1) was irrelevant." (PMID 40225869, 2025).